AGTR1 (angiotensin II receptor type 1)
Diseases named in the same sentence as AGTR1 in open-access papers (continued):
Sharing a sentence is not in itself a finding about the gene and the disease.
breast carcinoma (65 papers, 2006 to 2026). "Increased AGTR1 gene expression is associated with breast cancer, and ARBs inhibit mammary tumor formation in mice." (PMID 34285715, 2021). "AGTR1 is overexpressed in LumA- and LumB-subtype breast cancer, which is associated with aggressive features and decreased OS." (PMID 33644115, 2021). "Our analysis of the TCGA database is confirmatory that high AGTR1 expression is associated with luminal breast cancer and inversely correlated to HER2 expression." (PMID 28416734, 2017). "An insertion/deletion (I/D) polymorphism in intron 16 of ACE and a single nucleotide polymorphism (SNP) A1166C found in 3'untranslated region (UTR) of AGTR1 are reported to be implicated in various diseases; however their association with Breast Cancer (BCa) is still a topic of debate." (PMID 29460395, 2018). "Also, the AGTR1 gene was found to be implicated in other important cancers, i.e. colorectal or breast cancer." (PMID 29371888, 2018). "Previous studies demonstrate that the Angiotensin Receptor Type I (AT1R) is linked to breast cancer pathogenesis, with unbiased analysis of gene-expression studies identifying significant up-regulation of AGTR1, the gene encoding AT1R in ER+ve/HER2−ve tumors correlating with poor prognosis." (PMID 28416734, 2017). "Thus, we can conclude that the polymorphisms of ACE and AGTR1 genes could be considered as a risk factor of breast cancer, taking into consideration racial disparity." (PMID 34539580, 2021). "Indeed, we found that that AGTR1 overexpression, in both breast cancer patient samples and breast cancer cell lines, drives NF-κB activation and an associated NF-κB gene expression signature; as we expected, CARMA3, Bcl10, and MALT1 are each required for this to occur." (PMID 30158935, 2018). "In vivo, AGTR1 upregulation in breast cancer increased metastasis, while ARBs reversed these effects." (PMID 41408463, 2026). "In breast cancer, AGTR1-overexpressing MCF-7 cells exhibited elevated EMT markers (p-Smad, Smad4, Snail) as well as enhanced migration and invasion." (PMID 41408463, 2026). "AGTR1 is a poorly described gene in breast cancer that has recently gained attention as a potential target for drug repurposing." (PMID 38297001, 2024). "A literature review showed that AGTR1 has important effects on tumor growth, angiogenesis, inflammation, and immune function and plays a role in a variety of tumors, such as breast cancer, neuroendocrine tumors, and gliomas." (PMID 36983741, 2023). "AGTR1 promotes breast cancer lymph node metastasis by increasing the chemokine CXCR4/SDF-1α and tumor cell migration and invasion." (PMID 36983741, 2023). "One study showed that AGTR1 promotes lymph node metastasis and invasion in breast cancer by regulating CXCR4/SDF-1a." (PMID 36983741, 2023). "Previous studies have demonstrated the upregulation of AGTR1 in other cancer types (breast cancer, etc.)." (PMID 35910032, 2022). "Gene expression dataset analysis has revealed a strong upregulation of the GPCR family member AGTR1 that correlates with an NF-κB gene signature in a subset of luminal breast cancers." (PMID 35203553, 2022). "Amongst the tumor types in which NF-κB is activated through the CARD10-BCL10-MALT1 (C10BM) signalosome to promote tumorigenesis, there is a subset of angiotensin II receptor 1 (AGTR1)-positive luminal breast cancers with poor prognosis." (PMID 35203553, 2022). "It has been reported that AGTR1 expression is related with the growth, metastasis and poor prognosis in breast cancer, colorectal cancer and gastric cancer." (PMID 34496800, 2021). "High expression of AGTR1 was correlated with better survival in breast cancer, LUAD, and liposarcoma." (PMID 34671200, 2021). "In breast cancer, AGTR1 enhanced invasion, migration, and metastasis and also stimulated angiogenesis by increasing VEGF-A expression." (PMID 34095461, 2021).
breast carcinoma (continued). "According to the previous reports, AGTR1 exerts important functions in promoting the proliferation, invasion, migration and angiogenesis of cancer cells, such as glioma cells, breast cancer, cells and pancreatic cancer." (PMID 34496800, 2021). "The aim of this study was to analyze the capacity of losartan and AGTR-1 gene edition to modulate the EMT process in triple negative/metastatic mammary tumor cells, compared to existing treatment protocols such as carboplatin." (PMID 34947958, 2021). "A large-scale study of estrogen receptor-positive breast cancer tumors revealed an increase on AGTR1 mRNA expression." (PMID 32503281, 2020). "Vinson first reported in early 1995 that AGTR1 had a possible link with breast cancer and later confirmed this finding in many tumor types, such as ovarian cancer, prostate cancer, and pancreatic cancer." (PMID 31219799, 2019). "Quantification of AGTR1 by the HSCORE method suggested a significant increase in its expression in breast cancer tissues with lymph node metastasis (2.16 in LN+ vs. 1.52 in LN-), while similar results were observed in ER+ or HER2- samples." (PMID 31219799, 2019). "To explore these unanswered questions, in the present study, we sought to identify the AGTR1 expression profile from clinical breast cancer samples." (PMID 31219799, 2019). "To investigate the relationship and significance between AGTR1 and clinical pathological factors, we conducted IHC staining in breast cancer tissue sections, and positive AGTR1 was observed in 275 cases." (PMID 31219799, 2019). "Such therapeutic approach was proposed for breast cancer cases overexpressing AGTR1 and the effect of the drugs is known from in-vitro cell line experiments." (PMID 29371888, 2018). "Taken together, our study provided the first demonstration of a role for the C3BM complex in AGTR1 + breast cancer." (PMID 30158935, 2018). "Recent reports have shown elevated AGTR1 mRNA levels in breast cancer tissue and our radiolabelled-ligand binding data is supportive of this observation." (PMID 28416734, 2017). "AGTR1 is also involved in the invasion, migration or tumorigenesis of endometrial carcinoma and breast cancer via the up-regulation of VEGF." (PMID 28073349, 2017). "By using multiple independent breast cancer profiling studies, a MetaCOPA bioinformatics analysis has allowed prioritizing AGTR1 as a second ranked meta-outlier, immediately after HER2neu, which was identified as the most significant meta-outlier." (PMID 29240722, 2017). "Elevated expression of AGTR1, the gene encoding AT1R, has been linked to poor-prognosis and chemotherapy resistance in breast cancer, and lower progression free-survival outcomes in glioblastoma, colorectal cancer (CRC), hepatocellular carcinoma (HCC), and oesophageal squamous cell carcinoma (OSCC)." (PMID 41408463, 2026). "Overexpressed AGTR1 defines a subset of breast cancer and may confer sensitivity to AGTR1 antagonist losartan." (PMID 35910032, 2022). "The effect of genetic variation of ACE and AGTR1 genes on breast cancer in different ethnicity." (PMID 34539580, 2021). "Studies have also shown that AGTR1 may be a potential therapeutic target in early breast cancer with lymph node metastasis." (PMID 33644115, 2021). "AGTR1 was also highly expressed in ER+ breast cancer 63, pancreatic cancer 64, and gastric cancer." (PMID 34671200, 2021). "Nevertheless, the role of AGTR1 in breast cancer lymph node metastasis is still poorly understood." (PMID 34947958, 2021). "AT1R upregulation in ovarian cancer and increased expression of AT1R and ACE in prostate cancer, and AGTR1 in breast cancer; localized RAS presence in gastric cancer and its correlation with tumor spread and progression; demonstrate strong associations of RAS with various cancers." (PMID 33237942, 2020). "Our observations revealed that AGTR1 accelerated breast cancer cell migration and invasion." (PMID 31219799, 2019).
breast carcinoma (continued). "However, the role of AGTR1 on lymph node metastasis (LNM) in breast cancer, which correlates with tumor progression and patient survival, has not been examined." (PMID 31219799, 2019). "Our study indicated that inhibiting AGTR1 may be a potential therapeutic target for LNM in early-stage breast cancer." (PMID 31219799, 2019). "Furthermore, in 2009, our group participated in a multidisciplinary bioinformatic meta-analysis effort which identified AGTR1 as the second most high-scoring gene expression outlier in breast cancer cases." (PMID 30158935, 2018). "Previous studies found associations between AGTR1 A1166C and coronary artery disease and breast cancer, although genome-wide association studies (GWASs) found no significant AGTR1-associated signals." (PMID 29581855, 2018). "Since HER2 and AGTR1 overexpression are mutually exclusive in breast cancer, we hypothesized that these two receptors likely activate redundant signaling pathways, critical for driving pathogenesis." (PMID 30158935, 2018). "Furthermore, using a mouse model of AGTR1 + breast cancer, we found that suppression of C3BM signaling using an shRNA directed against Bcl10 results in significantly impaired tumor angiogenesis." (PMID 30158935, 2018). "ABCA1 expression was shown to be regulated by miR‐96 in breast cancer cell lines and AGTR1 was suggested to be a marker of resistance to neoadjuvant chemotherapy in HER2− breast cancer, whereas it was shown to be a therapeutic target in ER+ and ERBB2− breast cases." (PMID 29675884, 2018). "Indeed, we were able to demonstrate that conditioned media from AGTR1 + breast cancer cells drives endothelial chemotaxis through one or more of these secreted, C3BM-dependent factors." (PMID 30158935, 2018). "Indeed, overexpression of AGTR1 in breast cancer cells has been shown to promote tumor angiogenesis and epithelial mesenchymal transition (EMT), which together contribute to disease progression toward a malignant phenotype." (PMID 29240722, 2017). "A large-scale meta-analysis performed on 31 breast cancer profiling datasets has revealed over expression of the AT1 receptor gene (AGTR1) in 10–20% of invasive breast tumors, all of which were estrogen receptor positive (ER+) and human epidermal receptor 2 (HER2)-negative." (PMID 25741281, 2015). "We have also discussed different strategies for targeting AGTR1, and its ligand Angiotension II (Ang II), which might unravel unique opportunities for breast cancer prevention and treatment." (PMID 25981295, 2015). "Likewise, the chemokine receptor CXCR4 has multiple upstream mediators, with upregulation in renal cell carcinoma described in response to hypoxia inducible factor (HIF1a) and galectin 1, and in breast cancer with angiotensin II type I receptor (AGTR-1) and NF kappa B." (PMID 33927349, 2021). "Finally, we explored the potential mechanism of AGTR1-mediated cell migration and invasion and aimed to clarify whether losartan is beneficial for lymph node metastasis prevention and treatment in breast cancer." (PMID 31219799, 2019). "However, the role of AGTR1 in lymph node metastasis of breast cancer has rarely been described." (PMID 31219799, 2019). "Although patients with the AGTR1 A1166C A allele exhibit higher miR-155 and AGTR1 levels than those with the C allele, and this polymorphism is associated with coronary artery disease and breast cancer, current evidence does not support an association between AGTR1 A1166C and CKD in East Asians." (PMID 29581855, 2018). "In addition, our subsequent bioinformatic analyses demonstrated that AGTR1 overexpression correlates with aggressive clinical features in breast cancer, including a higher rate of lymph node metastasis, reduced responsiveness to neoadjuvant therapy, and reduced overall survival." (PMID 30158935, 2018).
breast carcinoma (continued). "Hence we can infer that the CBM signalosome may play a major role in AGTR1 mediated breast cancer pathogenesis, and MALT1 or Bcl10 inhibitors might prove as promising targets." (PMID 25981295, 2015). "Neutrophils acquire anti-tumor phenotypes in breast cancer under the influence of ACE inhibitors and AGTR1 antagonists, thereby suppressing tumor growth." (PMID 40564191, 2025). "In the selected key specific DEGs for Basal-subtype breast cancer, the altered expression of SOX11, PLK1, BUB1, OGN, COL4A6, AGTR1, and ADRB2 were significantly correlated with the prognostic survival of the patients." (PMID 33644115, 2021). "In this context, the aim of this study was to analyze the capacity of losartan treatment and AGTR-1 gene edition to modulate the EMT process in triple negative/metastatic canine and human mammary tumor cells." (PMID 34947958, 2021). "AGTR1 mediated cell movement and promoted lymph node metastasis by activating the FAK/RhoA pathway in early-stage breast cancer." (PMID 31781593, 2019). "Yet, we noted significant AGTR1 overexpression in nearly as many cases (approximately 20%) and demonstrated that AGTR1 and HER2 overexpression are mutually exclusive in breast cancer." (PMID 30158935, 2018). "In AGTR1 and HER2 positive breast cancer cell lines, NF-κB is activated upon stimulation with Angiotensin II or the HER2 ligand heregulin, respectively, in a CARMA3-dependent manner." (PMID 30214442, 2018). "AGTR1-positive breast cancers represent 15–20% of all breast cancers and HER2 positive breast cancers form 20–25% of all breast cancers." (PMID 30214442, 2018). "We also observed that angiotensin receptor type 1 (AGTR1) and ERBB2 are the nodal molecules in ninth and tenth IPA network and has relevance to breast cancer." (PMID 23216862, 2012). "In accordance with our findings, previous studies have shown that NOS3 and AGTR1 are related to the chemoresistance of cancer: NOS3 is related to oxaliplatin resistance in colorectal cancer cells, and AGTR1 is a marker of the drug resistance of breast cancer." (PMID 35513851, 2022). "SOX11, PLK1, BUB1, OGN, COL4A6, AGTR1, and ADRB2 may be involved in the recurrence of Basal-subtype breast cancer, and to some extent the PLK1, BUB1, OGN, COL4A6, AGTR1, and ADRB2 can be used as the specific prognostic markers for Basal-subtype breast cancer." (PMID 33644115, 2021). "The MetaCore pathway analysis suggested that “signal transduction: angiotensin II/angiotensin II receptor type 1 (AGTR1) signaling via Ras homolog family member A (RhoA) and c-Jun N-terminal kinase (JNK)” had a high correlation with breast cancers exhibiting PODXL2 expression." (PMID 32669966, 2020). "Moreover, the inhibition of AGTR1 decreased lymph node metastasis in orthotopic MDA-MB-231 and 4T1 breast carcinomas." (PMID 31219799, 2019). "More interestingly, LINC00665 can encode a special micropeptide (CIP2A-BP) to inhibit the progression of three negative breast cancers or act as a ceRNA that is involved in regulating the LINC00665/AGTR1/miR-34a-5p axis and other biological behaviours in glioma." (PMID 35174152, 2022). "Therefore, we hypothesized that the relationship between AGTR1 and CXCR4/SDF-1α has a great influence on lymph node metastasis in breast cancer." (PMID 31219799, 2019).
Stroke (46 papers, 2011 to 2026). Sudden impairment of blood flow to a part of the brain due to occlusion or rupture of an artery to the brain. "Also, an increased risk of stroke has been observed in patients with AGTR1 +1166 CC and AC genotypes, compared to AA genotype." (PMID 39591456, 2024). "Carriers of sensitive genotypes for AGTR1, CYP2D6*10, and ADRB1 taking sensitive drugs exhibited a significantly lower risk of stroke (ORs: 0.39, 0.67, 0.68; all P < 0.01)." (PMID 41968188, 2026). "Therefore, the association of CYP2D6∗10, CYP2C9∗3, AGTR1 (1166A > C), ACE (I/D), CYP3A5∗3, and NPPA (2238T > C) gene polymorphisms with stroke in hypertensive patients needs further studies." (PMID 38298191, 2024). "Regarding the AGTR1 (1166A > C) gene, studies revealed that its C allele was associated with increased BP in hypertensive patients; currently, there are no studies on its relationship with stroke in hypertensive patients." (PMID 38298191, 2024). "We did not establish an association of CYP2D6∗10, CYP2C9∗3, AGTR1 (1166A > C), ACE (I/D), CYP3A5∗3, and NPPA (2238T > C) gene polymorphisms with stroke susceptibility." (PMID 38298191, 2024).
Insulin resistance (45 papers, 2009 to 2025). Increased resistance towards insulin, that is, diminished effectiveness of insulin in reducing blood glucose levels. "The polymorphism of AGTR1 is proposed to affect the insulin resistance by altering the response to angiotensin II signaling." (PMID 32382544, 2020). "Furthermore, a recent study has shown that tripeptides with ACE inhibitory activity improved insulin resistance in rat-derived L6 skeletal muscle cells, at least partially via reduced AGTR-1 expression and attenuating reactive oxygen species (ROS) in L6 cells." (PMID 36112580, 2022). "Besides, it is reported that the receptor of AGTR1 is activated on liver cells in initiation of insulin resistance, which further enlarges the activation of hepatocellular NF-κB signaling and NF-κB signaling is responsible for negative crosstalk with insulin." (PMID 32382544, 2020). "Thus, APOAV overexpression may prevent the insulin resistance in liver cells by mediating the genes such as AGTR1 and P2RY2." (PMID 32382544, 2020). "AGTR1 (angiotensin II receptor type 1) is a key player in the renin-angiotensin system (RAS) that can increase blood pressure and insulin resistance while also inhibiting lipolysis, maintaining energy homeostasis, and reducing inflammation." (PMID 38246999, 2024).
myocardial infarction (45 papers, 2013 to 2026). Gross necrosis of the myocardium, as a result of interruption of the blood supply to the area, as in coronary thrombosis. "Similarly, among north Indian patients with ID + DD ACE and 1166AC + CC AGTR1, the combined genotype had a much higher risk of acute myocardial infarction than with II ACE and the 1166AA AGTR1 combined genotype." (PMID 35886041, 2022). "Specifically, miR-199a-5p targets AGTR1, diminishing early oxidative damage post-myocardial infarction, and MARK4, which influences long-term myocardial contractility and enhances cardiac function." (PMID 38956062, 2024). "The mechanistic studies confirmed that miR199a-5p could protect the heart from myocardial infarction injury by controlling the AGTR1/NOX4 and MARK4/VASH2/dTyr-tub pathways." (PMID 38956062, 2024). "It was shown to improve cardiac function in mice post-myocardial infarction by enhancing mitophagy through the Pink1/Parkin signaling pathway, and to improve cardiac function in STZ-induced diabetic mice by promoting AGTR1/TRPV1-mediated autophagy." (PMID 41178953, 2025).
Myocardial fibrosis (40 papers, 2011 to 2025). "AGTR1-Agtr1-induced myocardial fibrosis is either directly mediated by the angiotensin II stimulation of AGTR1-Agtr1 or indirectly by the AGTR1-Agtr1-mediated induction of transforming growth factor beta 1, TGFB1-Tgfb1." (PMID 35203304, 2022). "The sensitisation of Agtr1 by RKIP promotes myocardial fibrosis." (PMID 35203304, 2022).
renal fibrosis (40 papers, 2012 to 2025). A final common manifestation of a wide variety of chronic kidney diseases characterized by glomerulosclerosis and tubulointerstitial fibrosis. "The binding of angiotensin II to AGTR1 leads to ROS production and subsequently to cellular senescence associated with mitochondrial dysfunction, hypertrophy, inflammation, and renal fibrosis." (PMID 39273282, 2024).